MMP19 (matrix metallopeptidase 19)
Diseases named in the same sentence as MMP19 in open-access papers (continued):
Sharing a sentence is not in itself a finding about the gene and the disease.
tumor (continued). "SPP1+ macrophages from tumor tissues showed high expression of MMP9, MMP12, MMP14, and MMP19, which could contribute to the degradation of the basement membrane for the invasion of tumor cells." (PMID 38347955, 2023). "Furthermore, our results indicate that, of the 10 selective tumor-promoting genes of macrophages, only MMP19 and SIRPα can predict ICB responses in ICCs." (PMID 36158683, 2022). "MMP19 is a key modulator in many cellular and developmental processes such as cell migration and transformation; it was reported to act as both tumor promotor and tumor suppressor." (PMID 29967069, 2018). "In contrast, the MMP19 transcript, whose relevant protein is associated with invasion and tumor progression, was not up-modulated in EGF-stimulated EOC cells." (PMID 23889749, 2013). "As all reported angiostatin species exhibit the biological activities of angiostatin isolated from plasma (e.g. inhibition of endothelial proliferation, angiogenesis, and tumor growth and metastasis), the angiostatin-like fragments generated by MMP-19 should also have such biological activities." (PMID 21787393, 2011). "A clear predominant staining of tumor cell's cytoplasm was found for MMP-19." (PMID 19531263, 2009). "However, MMP-19, which is up-regulated in various cancer tissues, facilitates tumor invasion." (PMID 27227769, 2016). "MMPs are key molecules of tumor cell invasion, including EOCs and, since the majority of samples were advanced stage EOCs, MMP19 could be a new player in the dissemination of these tumors and experiments are now ongoing to test its presence and role in advanced stage EOCs." (PMID 23889749, 2013). "MMP-19 promotes tumor cell proliferation, invasion, epithelial-mesenchymal transition (EMT), angiogenesis and metastasis in the tumor microenviroment 49,50." (PMID 41362730, 2026). "These MMP19+ TAMs form a ring-shaped barrier structure surrounding the cancer cells, thereby inhibiting the infiltration of CD8+ T cells into the tumor interior and ultimately contributing to the resistance of LC-BoM to immunotherapy." (PMID 41362730, 2026). "This treatment disrupts the ring barrier structure of MMP19+ TAMs, facilitating the infiltration of CD8+ T cells into the tumor interior, and consequently enhances the sensitivity of LC-BoM to immunotherapy." (PMID 41362730, 2026). "ZEB1-AS1 in OC was shown to have tumor-suppressor properties and the ability to restore chemosensitivity to PTX- and DDP-resistant A2780/R OC cells and to silence MMP19 in ZEB1-AS1-overexpressing cells." (PMID 39519394, 2024). "MMP9_macro expressed genes related to inflammatory chemokines (CXCL2, CXCL3, CXCL8) and genes like MMPs (MMP19, MMP9), which play an important role in tumor tissue remodeling." (PMID 35935940, 2022). "We also evaluated the protein level of MMPs in our patients and measured the expression level of MMP1–MMP3, MMP7–MMP9, MMP11, MMP12, MMP14, MMP17, MMP19, and MMP28 in their tumor tissue and adjacent normal tissue by Western blot." (PMID 34804973, 2021). "Key oncogenes showed differing expression profiles depending on which region of the tumor was analyzed, with lower expression of SOX2 or elevated expression of SERPINE1 and MMP19 in 5-ALA/FACS-positive cells, for example." (PMID 32904996, 2020). "During this process, genes such as SOD2, MMP19, SLC2A3, and SLPI were also upregulated, all of which were related to the invasion and migration of tumor cells." (PMID 31487431, 2019). "Over the last decade, however, tumor suppression functions have paradoxically been proposed for a few members of the MMP family, such as MMP19." (PMID 29967069, 2018). "Our current study showed MALAT-1 knockdown modulated the expression of MMP13 and MMP19, members of the matrix metalloproteinase (MMP) family of proteins that are involved in altered extracellular matrix metabolism, tumor progression and metastasis." (PMID 27227769, 2016).
tumor (continued). "The model diagram indicated the absence of the phenomenon where MMP19+ TAMs form a ring around tumor cells in DMAb-treated LC-BoM samples." (PMID 41362730, 2026). "Furthermore, our investigation revealed a notable upregulation of several matrix metalloproteinases (MMPs) in tumor-infiltrating macrophages, including MMP9, MMP12, MMP19, ADAM8, ADAM9, and ADAM17." (PMID 38254761, 2024). "Interestingly, the levels of SRC and PPARB/D expression were highly and significantly correlated in these tumours, as were the expression levels of PPARB/D andTGFB1 and MMP19, respectively, and to a lesser extent, MMP2, VEGFA, VIM and SNAI1." (PMID 24203162, 2014). "In an immunohistochemical study comparing normal breast tissue and mammary gland tumors, Djonov and colleagues found MMP-19 to be expressed in all benign lesions, whereas no expression was found in tumor tissue." (PMID 19531263, 2009). "Furthermore, cells in the myCAF-(F-POSTN) and iCAF-(F-ALPL) groups expressed high levels of matrix metalloproteinases (MMPs; e.g., MMP2, MMP14, MMP23B, and MMP19), indicating that these cells are involved in degradation of the basement membrane and ECM to facilitate tumor metastasis." (PMID 40319103, 2025). "We found that the expressions of MMP-14, MMP-19 and MMP-2 were upregulated in BCL individuals compared to CC, during which fibroblasts and myeloid cells displayed abundant MMP expression, indicating that the MMPs gene set could participate in inhibits tumor progression of CC." (PMID 39247608, 2024). "In terms of spatial distribution, in LC-BoM tissues without DMAb treatment, a distinct ring of MMP19+ TAMs was observed surrounding the tumor cell nests, which acts as a barrier to prevent CD8+ T cells from infiltrating into the inner regions of the tumor." (PMID 41362730, 2026). "MSGN1, ISM2, HAS1, RETN, MMP19, C1QTNF1, and F13A1 were all involved in the regulation of tumors, but their involvement in the regulation of tumor immunity is not clear." (PMID 34177903, 2021).
cancer (32 papers, 2009 to 2026). A tumor composed of atypical neoplastic, often pleomorphic cells that invade other tissues. "We found that MMP19 expression was significantly upregulated in cancer tissues relative to the normal controls, and that high MMP19 expression was associated with inferior clinical characteristics." (PMID 31088409, 2019). "The Mmp-19-deficient mouse model not only is considered to negatively regulate the early steps of tumor angiogenesis and invasion but is also thought to be associated with decreased susceptibility to cancer." (PMID 25352026, 2015). "Mmp19, part of the metalloproteinase family implicated in cancer, has been reported to induce epithelial cell migration, playing an important role in the early stage of cancer." (PMID 19936259, 2009). "mRNA expression levels of MMP-12, MMP-13, MMP-14, and MMP-19 in the cervical tissue of patients with cancer were greater than that observed in the control (p = 0.045, p = 0.025, p = 0.003, and p = 0.025, respectively)." (PMID 39247608, 2024). "Several studies have demonstrated that MMP1, MMP2, MMP9, MMP13 and MMP19 in some cancer tissues such as NSCLC or gastric cancer are all raised, and these MMP members can degrade basement membrane and open the channel for cancer’s invasion and metastasis." (PMID 38560562, 2024). "Twenty ICC and 20 paracancer tissue samples collected between July 1, 2016 and July 1, 2019 from The Affiliated Cancer Hospital of Zhengzhou University were tested for the expression of MMP19 and SIRPα." (PMID 36158683, 2022). "When we looked at extracellular proteases, matrix metallo-proteases in particular, we observed that Mmp-14, Mmp-19 and Mmp-8 were also up-regulated in SSMs in cancer." (PMID 34168645, 2021). "Previous studies have also shown that MMPs are involved in cancer metastasis and invasion, so we also investigated the influence of MMP-19 and MMP-20 on cell invasion abilities using the Boyden chamber method." (PMID 31406154, 2019). "The results indicated that MMP19 expression was significantly up-regulated in cancer tissues than in normal controls (P < 0.05)." (PMID 31088409, 2019). "According to the past studies, MMP19, ADAMTS1and MMP13 genes are closely associated with the metastasis and development of malignant tumors." (PMID 27227769, 2016). "MMP-11 (stromelisin-3 or ST3) and MMP-19 are important in cancer cell proliferation and demonstrated the opposite roles in studies of genetic mouse models." (PMID 25352026, 2015). "MMP19 is reportedly involved in the progression and metastases of various cancers, but its role in CRC remains unknown." (PMID 31088409, 2019). "Further studies found MMP-19 and MMP-20 high expressions could cause drug resistance and cancer invasion, providing potential molecular mechanisms for the poor prognosis caused by high MMP-19 and MMP-20 expressions." (PMID 31406154, 2019). "Interestingly, several MMPs featured inconsistent survival trends across cancer types with MMP19 showing opposite trends when comparing renal papillary (KIRP) with renal clear cell (KIRC)." (PMID 31200666, 2019). "Interestingly, three of these genes, MMP19, ADAMTS1, and MMP13, have been previously implicated in the regulation of angiogenesis, extra-cellular matrix, cell adhesion, and cancer progression." (PMID 27227769, 2016). "The association of genetic polymorphisms in the MMP-11 and MMP-19 with cancer risk has not been investigated; only the results of MMP-19 expression have been described as associated with cancer processes." (PMID 25352026, 2015). "Additionally, seven proteins: Cacna1c, Vcl, Fcgbp, Mmp19, Lyz2, Eef1a1, and Gapdhs had cancer-only peptides." (PMID 19936259, 2009). "However, we found MMP-19 protein to be higher expressed in cancer tissue although its mRNA was equally expressed in all analyzed samples." (PMID 19531263, 2009).
cancer (continued). "Furthermore, we explored the relationship between MMP19 expression and cancer prognosis using our data to determine whether MMP19 can serve as a valuable prognostic predictor in CRC patients." (PMID 31088409, 2019). "MMP-19, or stromelysin-4 or RASI-1, is an ECM proteinase located on chromosome 12 and is involved in tissue remodeling, fibrosis, and cancer." (PMID 41281748, 2025). "In addition, we found that macrophage subpopulations (clusters 1, 5, 7, 8, and 9) from cancer tissues expressed a certain number of immunosuppressive genes, such as VEGFA, MMP14, MMP19, S100A2, APOE, HMOX1, SLAMF7, SIRPα, LAG3 and IL18." (PMID 36158683, 2022). "Distant metastases and recurrence are two main reasons for cancer-related death; thus, it was not surprising that high MMP19 expression was correlated with a poor prognosis in CRC." (PMID 31088409, 2019). "Other members of the MMP family (MMP15, MMP16, MMP19, and MMP27) showed no differential expression between pancreatic normal and cancer tissues." (PMID 37821678, 2023). "MMP-19 and MMP-20 knockdown did not increase Cov362 resistance to Paclitaxel (both p > 0.05), which might due to the fact that different molecular mechanisms are involved in the anti-cancer effects of these drugs." (PMID 31406154, 2019).
MMP19 also shares sentences with these, for which no sentence is quoted: heart failure (8 papers); Hyperkalemia (7); diabetes (5); Hypertension (5); pancreatic cancer (5); kidney disease (4); infection (3); acute myocardial infarction (2); atherosclerosis (2); chronic kidney disease (2); diabetic kidney disease (2); glioblastoma (2); renal cell carcinoma (2); tendinopathy (2); type 2 diabetes (2); acute kidney injury (1); Alport syndrome (1); cardiovascular disease (1); colorectal tumour (1); congestive heart failure (1); coronary artery disease (1); cutaneous melanoma (1); emphysema (1); esophageal cancer (1); Fasciola infection (1); glomerulonephritis (1); glucose metabolism disorder (1); Hepatic steatosis (1); hepatocellular carcinoma (1); Hypercholesterolemia (1).
A further 18 diseases each share a sentence with MMP19 in 1 paper.